TOP3A (DNA topoisomerase III alpha)
Diseases named in the same sentence as TOP3A in open-access papers (continued):
Sharing a sentence is not in itself a finding about the gene and the disease.
triple-negative breast carcinoma (1 paper, 2023). An invasive breast carcinoma which is negative for expression of estrogen receptor (ER), progesterone receptor (PR), and human epidermal growth factor receptor 2 (HER2). "Concerning a gene and its association with cancer progression, it was observed that the TOP3A mutation is a prognostic factor for adjuvant chemotherapy in triple-negative breast cancer." (PMID 37298600, 2023). "Five other members belonging to the family of homologous recombination repair genes were upregulated by PAC in triple-negative breast-cancer cells (RAD54L, XRCC3, RAD51D, FEN1, and TOP3A) but only RAD54L is common in both types of cell lines (MCF-7 and MDA-MB-231)." (PMID 37298600, 2023).
cancer (16 papers, 2009 to 2024). A tumor composed of atypical neoplastic, often pleomorphic cells that invade other tissues. "TOP3A is associated with homology-directed repair and methylation may lead to increased chromosomal instability, a hallmark of cancer." (PMID 37669321, 2023). "Survival analysis showed that the CNVs of TOP2B in 13 cancer types, TOP3B in 7 cancer types, TOP2A in 6 cancer types, TOP1MT in 6 cancer types, TOP3A in 5 cancer types and TOP1 in 5 cancer types significantly correlated with overall prognosis." (PMID 36288358, 2022). "Correlation analysis indicated that the mRNA expressions of topoisomerase family genes were positively correlated with their copy number levels in most cancers, such as TOP3A in PAAD and TOP2A in UCEC." (PMID 36288358, 2022). "Across cancer types, TOP3A was found to be commonly methylated in BLCA, COAD, STAD, and UCEC." (PMID 37669321, 2023). "Thus, genetic variants of BLM and proteins that form complexes with BLM, such as TOP3A and RMI1, might affect cancer risk as well." (PMID 19432957, 2009). "We demonstrated the functional significance of these results by showing that TOP3A overexpression in ALT cancer cells countered ATRX‐mediated ALT inhibition and that TOP3A knockdown disrupted the ALT phenotype in ATRX‐wt cells." (PMID 35920001, 2022). "The biologic role and the prognostic effect of TOP3A and TOP3B in cancer patients are still poorly understood." (PMID 28355294, 2017). "The biologic role of TOP3 remained poorly understood, as well as the prognosis value of TOP3A and TOP3B in cancer patients." (PMID 27315793, 2016). "GEPIA2 database analysis of 33 cancer types showed the following top 10 ALKBH5-related genes: GID4 (R=0.71), TOP3A (R=0.67), MAPK7 (R=0.66), NT5M (R=0.61), FLII (R=0.59), ZNF18 (R=0.57), DRG2 (R=0.57), COPS3 (R=0.56), MED9 (R=0.56) and PRPSAP2 (R=0.56) (all P<0.0001)." (PMID 35444654, 2022).
tumor (10 papers, 2016 to 2024). "Other key repair genes such as FEN-1, LIG1, XPA and TOP3A were also found downregulated indicating reduced tumor progression, chemo-resistance, alternative end-joining (Alt-EJ) and nucleotide excision repair (NER)." (PMID 34680264, 2021). "Our findings revealed that the expression levels of TOP3A, SRC, and BUB3 were significantly elevated in the tumor groups of both the TCGA and GEO cohorts." (PMID 38825615, 2024). "For TOP3A (0 vs. 6) and TOP3B (0 vs. 2), although limited, all datasets with any expression changes, showed gene downregulation in tumor vs. normal tissues." (PMID 27315793, 2016).
mitochondrial disease (3 papers, 2021 to 2024). "In order to characterise the effects of pathological variants upon different aspects of TOP3A function, we used Sf9 insect cells to express and purify wild‐type (WT) TOP3A, as well as all missense variants found in mitochondrial disease patients reported here." (PMID 37013609, 2023). "We present a comprehensive characterisation of the effect of TOP3A variants, from individuals with mitochondrial disease and Bloom‐like syndrome, upon mtDNA maintenance and different aspects of enzyme function." (PMID 37013609, 2023). "We report cases of adult‐onset mitochondrial disease caused by pathological variants in the topoisomerase TOP3A, which localises both to mitochondria and nucleus." (PMID 37013609, 2023). "Here, in addition to the single case that we previously reported, we describe a further cohort of 10 individuals from 8 families with an adult‐onset mitochondrial disease resulting from previously unreported bi‐allelic variants in TOP3A." (PMID 37013609, 2023). "The identification of so many new families strongly argues for the inclusion of TOP3A as a mitochondrial disease gene associated with adult mitochondrial disease characterised by a PEO phenotype and Mendelian inheritance." (PMID 37013609, 2023). "In this work, we describe 11 individuals from 9 families with an adult‐onset mitochondrial disease resulting from bi‐allelic TOP3A gene variants." (PMID 37013609, 2023). "The p.Leu37Val and p.Met575Val variants of TOP3A, found in the cohort of mitochondrial disease patients, were unable to gel shift the labelled oligonucleotide, indicating a significant loss of DNA‐binding activity." (PMID 37013609, 2023). "The loss of mitochondrial topoisomerase activity leads to defects in mitochondrial function, and variants in the dual-localized type IA topoisomerase TOP3A have also been reported to cause human mitochondrial disease." (PMID 34547213, 2021). "Missense variants in TOP3A were initially reported in a single individual with an adult-onset mitochondrial disease characterized by progressive external ophthalmoplegia and cerebellar ataxia." (PMID 34547213, 2021). "Based on these results, we suggest a model whereby the overall severity of the TOP3A catalytic defect determines the clinical outcome, with milder variants causing adult‐onset mitochondrial disease and more severe variants causing a Bloom‐like syndrome with mitochondrial dysfunction in childhood." (PMID 37013609, 2023). "These combinations of variants displayed an intermediate level of activity relative to the single variants alone and confirms that patients with TOP3A‐related mitochondrial disease in this cohort retain at least one allele that displays a detectable level of activity." (PMID 37013609, 2023).
cardiac disease (1 paper, 2024). "Recessive TOP3A variants either cause mtDNA depletion and severe multisystemic neonatal disease, or adult-onset PEO, ptosis, and proximal myopathy, with peripheral neuropathy and cardiac disease, in association with multiple mtDNA deletions." (PMID 38804971, 2024).
TOP3A also shares sentences with these, for which no sentence is quoted: acute myeloid leukemia (2 papers); Fanconi anaemia (2); infection (2); Adult onset (1); amyotrophic lateral sclerosis (1); anemia (1); Ataxia (1); ataxia-telangiectasia-like disorder (1); bone tumors (1); cyst (1); diffuse intrinsic pontine glioma (1); hepatitis C (1); inherited diseases (1); lung squamous cell carcinoma (1); non-small cell lung carcinoma (1); ovarian carcinoma (1); sarcomatoid carcinoma of lung (1); Werner syndrome (1).